MVK (mevalonate kinase)
Diseases named in the same sentence as MVK in open-access papers (continued):
Sharing a sentence is not in itself a finding about the gene and the disease.
cancer (13 papers, 2017 to 2025). A tumor composed of atypical neoplastic, often pleomorphic cells that invade other tissues. "Studies have indicated that the mevalonate pathway involved in cholesterol synthesis is closely related to cancer development by producing a variety of raw materials necessary for protein modification, and an increased mevalonate kinase requirement has become a hallmark of cancer progression." (PMID 37537560, 2023). "SREBP-2 binds to the sterol regulatory elements in the promoters of genes such as HMGCR and mevalonate kinase (MVK) to activate and regulate the enzymes in mevalonate pathway, involving in the progression of various cancers." (PMID 35790992, 2022). "At the same time, MVK inhibition would deplete downstream metabolites such as FPP and GGPP in cancer cells." (PMID 30298120, 2018). "The expression levels of EP400, HMGB2, CDK1, PPARG, and MVK were found to be significantly correlated with HMGA1 expression level in both analyzed cancer subtypes but not in non-cancerous tissue of the lung." (PMID 35805937, 2022).
infection (5 papers, 2018 to 2021). The state of being infected such as from the introduction of a foreign agent such as serum, vaccine, antigenic substance or organism. "Peripheral blood mononuclear cell (PBMC)-derived macrophages infected with mevalonate kinase-overexpressing parasites showed an increase in intracellular parasite burden in comparison to infection with vector control parasites." (PMID 33981628, 2021). "We report an up-regulation in host MVK, a key enzyme in both sterol and isoprenoid synthesis, following infection of enteroids with T. gondii RH." (PMID 31555604, 2019). "For example, mevalonate kinase (MVK), a key enzyme in both sterol and isoprenoid synthesis, was upregulated following infection with T. gondii RH." (PMID 31555604, 2019). "Both MVK and HMGCR are expressed in T. evansi during the course of infection in animals, and therefore are potential targets for therapeutic drug design." (PMID 30042928, 2018).
tumor (5 papers, 2019 to 2025). "Consistent with the rate decrease, tumor mRNA and protein expression of HMGCS1, MVK, MVD, and SQLE was also significantly downregulated by XY018 or its combination with statin." (PMID 31604910, 2019).
genetic disorder (3 papers, 2024 to 2026). "HIDS is a genetic disease that arises from mutations in the mevalonate kinase (MVK) gene." (PMID 39274425, 2024). "BACKGROUND: Mevalonate kinase deficiency (MKD) is a rare genetic disorder, resulting in the lack of the mevalonate kinase enzyme (MVK), which is involved in the biosynthesis of cholesterol, non-sterol isoprenoids, and coenzyme Q10 (CoQ10)." (PMID 41680896, 2026).
metabolic disorder (3 papers, 2022 to 2025). "The positive associations with MVK, an enzyme essential for the mevalonate pathway and linked to metabolic disorders, could support the important role of metabolic pathways, and neuroinflammatory processes in the disease process." (PMID 40289873, 2025).
immune disorder (1 paper, 2013). "However, patients with mutations in the mevalonate kinase gene (e.g. hyper-IgD syndrome) may respond differently to the treatment with statins, although the prevalence rate of this immune disorder is very low." (PMID 24147031, 2013).
MVK also shares sentences with these, for which no sentence is quoted: Majeed syndrome (3 papers); Methylmalonic aciduria (3); primary immunodeficiencies (3); AIDS (2); Blau syndrome (2); chronic infantile neurological cutaneous articular syndrome (2); juvenile idiopathic arthritis (2); Muckle-Wells syndrome (2); Obesity (2); acne (1); adenitis (1); adult-onset Still disease (1); Arthritis (1); autosomal dominant familial periodic fever (1); autosomal recessive inherited disorder (1); breast carcinoma (1); cardiovascular diseases (1); cataract (1); cerebellar ataxia (1); CHILD syndrome (1); CK syndrome (1); depression (1); desmosterolosis (1); developmental delay (1); dyslipoproteinemic corneal dystrophy (1); familial cold autoinflammatory syndrome (1); familial cold autoinflammatory syndrome 4 (1); Fanconi anemia (1); Gaucher disease (1); generalized pustular psoriasis (1).
A further 30 diseases each share a sentence with MVK in 1 paper.